PARVB (parvin beta)
Description:
Adapter protein that plays a role in integrin signaling via ILK and in activation of the GTPases CDC42 and RAC1 by guanine exchange factors, such as ARHGEF6. Is involved in the reorganization of the actin cytoskeleton and formation of lamellipodia. Plays a role in cell adhesion, cell spreading, establishment or maintenance of cell polarity, and cell migration.
Synonyms: CGI-56
Tractability: Antibody: its Gene Ontology location is reachable by antibodies, with high confidence; UniProt places it where antibodies can reach, with medium confidence; the Human Protein Atlas places it where antibodies can reach. PROTAC: ubiquitination databases record sites on it; its protein half-life has been measured.
Gene: Protein-coding gene on chromosome 22 (43,999,211 to 44,172,939, forward strand). Ensembl gene ENSG00000188677.
Subcellular location: Cell junction, focal adhesion; Cell membrane; Cytoplasm, cytoskeleton; Cell projection, lamellipodium; Cytoplasm, myofibril, sarcomere; Cytoplasm, myofibril, sarcomere, Z line
Subcellular location (Human Protein Atlas): Actin filaments; Plasma membrane
Pathways (Reactome):
Cell-Cell communication: Cell-extracellular matrix interactions; Regulation of cytoskeletal remodeling and cell spreading by IPP complex components
Gene Ontology:
Molecular function: protein binding; actin binding
Biological process: actin cytoskeleton organization; cell projection assembly; establishment or maintenance of cell polarity regulating cell shape; lamellipodium assembly; substrate adhesion-dependent cell spreading; actin filament-based process; cell adhesion; plasma membrane bounded cell projection assembly
Cellular component: actin cytoskeleton; focal adhesion; lamellipodium; plasma membrane; cytoplasm; cytosol; cytoskeleton; sarcomere; Z disc
Genetic constraint (gnomAD): Loss-of-function variants: 25 observed, 27.55 expected, observed/expected ratio (o/e) 0.91, 90% interval 0.66 to 1.27. The upper end of that interval is the gene's LOEUF score, 1.27, which puts it in group 5 of 6, group 1 being the genes least tolerant of losing a copy. Missense variants: 334 observed, 324.23 expected, observed/expected ratio (o/e) 1.03, 90% interval 0.94 to 1.13. Synonymous variants: 139 observed, 131.8 expected, observed/expected ratio (o/e) 1.05, 90% interval 0.92 to 1.21.
Homologues: Orthologues: guinea pig PARVB (93% identical), mouse Parvb (91% identical), chimpanzee PARVB (91% identical), rat Parvb (90% identical), tropical clawed frog parvb (83% identical), pig PARVB (83% identical), dog PARVB (79% identical), macaque PARVB (74% identical), zebrafish parvb (73% identical), Drosophila melanogaster parvin (59% identical), Caenorhabditis elegans pat-6 (49% identical). Paralogues in human: PARVA (74% identical), PARVG (38% identical).
Diseases named in the same sentence as PARVB in open-access papers:
PARVB is named in the same sentence as 22 diseases in open-access papers, as found by Europe PMC text mining. Sharing a sentence is not in itself a finding about the gene and the disease. The quoted sentences say what the papers report.
breast carcinoma (4 papers, 2009 to 2022). "As PARVB introduction was reported to suppress cellular growth of breast cancer cells with decreased Akt phosphorylation, Parvb introduction in MEF also decreased phosphorylation of Akt in exposure to a growth factor or serum." (PMID 22072987, 2011). "PARVB, encodes beta-parvin, which negatively regulates integrin-linked kinase (ILK) activity in breast cancer cells." (PMID 19924294, 2009).
colorectal cancer (4 papers, 2010 to 2022). A primary or metastatic malignant neoplasm that affects the colon or rectum. "Overexpression of PARVB has been associated with poor prognosis in human colorectal cancer and tongue squamous cell carcinoma." (PMID 34568031, 2021). "β-Parvin (PARVB) is overexpressed in human colorectal cancer and tongue squamous cell carcinoma, and is closely associated with tumor progression." (PMID 34568031, 2021). "Importantly, overexpression of nuclear β-catenin and downregulation of E-cadherin were observed in human colorectal cancer featuring highly expression of PARVB protein." (PMID 34568031, 2021).
tongue squamous cell carcinoma (3 papers, 2021 to 2024). A squamous cell carcinoma that arises from the tongue. "Studies indicate that overexpression of PARVB can facilitate the endogenous growth and metastasis of tongue squamous cell carcinoma through enhanced tumor migration." (PMID 38643300, 2024). "Previous studies have demonstrated that PARVB overexpression may promote endogenous growth and metastasis of tongue squamous cell carcinoma by enhancing tumor migration." (PMID 37716978, 2023).
glioblastoma (2 papers, 2021 to 2024). The most malignant astrocytic tumor (WHO grade IV). "In tumor studies such as glioblastoma multiforme, hypomethylated and highly expressed PARVB may be involved in the process of epithelial to mesenchymal transition (EMT) and significantly associated with poor prognosis, making it a potential target for tumors." (PMID 38172938, 2024).
non-alcoholic fatty liver disease (2 papers, 2015 to 2024). "Studies on abnormal PARVB promoter methylation have primarily focused on tumor and non-alcoholic fatty liver disease." (PMID 38172938, 2024).
Alzheimer disease (1 paper, 2022). A progressive, neurodegenerative disease characterized by loss of function and death of nerve cells in several areas of the brain leading to loss of cognitive function such as memory and language. "Genes encoding the cytoskeleton-interacting proteins PLEC and PARVB are risk factors for Alzheimer’s disease, and genetic variants of PLEC and SYNE1 are high-risk alleles for bipolar disorder." (PMID 36400935, 2022).
encephalitis (1 paper, 2025). An acute inflammatory process affecting the brain parenchyma. "In addition, we validated the upregulation of mRNA GUCY1A3, IDS, PARVB, and TROVE2 in anti-NMDAR encephalitis via PCR." (PMID 40948637, 2025).
liver cancer (1 paper, 2019). An epithelial or non-epithelial malignant neoplasm that arises from the liver. "At the 22q region, PNPLA3 incorporate mostly in the phospholipid metabolism and lipase activity pathways, SAMM50 enriched in the mitochondrial assembly pathway (GO cellular components), and PARVB enriched in the liver cancer pathway." (PMID 31311600, 2019).
oral cancer (1 paper, 2021). "In PARVB knockdown oral cancer cells, loss of fibroblast-like structures at the wound edge was found." (PMID 34568031, 2021).
renal adysplasia (1 paper, 2022). "The SULT4A1, PARVB, SCO2, and UPK3A genes are associated with neurological features, macrocephaly/hypotonia, oculopathy, and renal adysplasia, respectively." (PMID 36118903, 2022).
steatosis (1 paper, 2015). Increased lipid within the cytoplasm of cells. "On the other hand, the steatosis grade was significantly higher in patients with PNPLA3 CG/GG and PARVB AG/GG than in those with PNPLA3 CC (P < 0.001) and PARVB GG (P = 0.001), respectively." (PMID 26352693, 2015).
tumor (8 papers, 2010 to 2024). "Our study found that patients with higher PARVB tumor expression had significantly worse survival rates." (PMID 34568031, 2021). "PARVB is involved in cell adhesion and survival and also plays an important role in angiogenesis which promotes tumor growth in cancers." (PMID 27434648, 2016). "According to Kaplan–Meier analysis with the log-rank test, tumour grade, pT stage, tumour size, vascular invasion and downexpression of ParvB level were unfavourable factors for disease-specific survival of patients with UUT-UC." (PMID 20736946, 2010). "This study showed the T-stage factor corresponding to the depth of tumour invasion; low ParvB expression corresponding to the ability of cell invasiveness and vascular invasion are the independent prognostic factors for disease-free survival." (PMID 20736946, 2010). "Downexpression of ParvB level in UUT-UC correlated with tumour stage, and was an independent unfavourable prognostic factor for disease-specific survival of patients with UUT-UC." (PMID 20736946, 2010). "This study showed that ParvB expression levels reversely correlated with tumour grade, tumour stage and tumour size." (PMID 20736946, 2010). "These clinical findings were matched to molecular results: low ParvB expression increased tumour cell growth and invasion." (PMID 20736946, 2010). "Our results underscore ParvB as a regulator of cell growth and migration, which has important implications given that cell proliferation and invasiveness are related to tumour aggression." (PMID 20736946, 2010). "In the TCGA-HNSC cohort, we found that ACTB, MAP2K1, PARVB, and PDGFA were upregulated in tumour tissues, suggesting that gene expression may be associated with tumourigenesis." (PMID 37691922, 2023). "In addition, we found that the expression of some NRGs had positive correlations with tumor-infiltrating immune cells, including PARVB, SPP1, and LYZ." (PMID 37716978, 2023). "Our results show that ParvB is downregulated in UC tumours at both mRNA and protein levels." (PMID 20736946, 2010). "Downregulation of ParvB protein levels were detected in seven of 10 tumours." (PMID 20736946, 2010). "Parvin-β (ParvB), a potential tumour suppressor gene, is a focal adhesion protein." (PMID 20736946, 2010). "Moreover, we have shown that ParvB protein levels in advanced UUT-UC tumours are lower than those in superficial UUT-UC tumours." (PMID 20736946, 2010). "The downregulation of ParvB expression in the UUT-UC tumours prompted us to investigate whether dysregulation of ParvB affects in cell growth and invasion." (PMID 20736946, 2010). "Furthermore, ParvB protein levels were decreased by >50% in four of seven tumours." (PMID 20736946, 2010). "Comparison of ParvB expression levels revealed downregulation in UC specimens relative to normal urothelium, with the lowest level of ParvB expression in muscle invasive tumours relative to non-muscle invasive tumour." (PMID 20736946, 2010).
cancer (7 papers, 2010 to 2023). A tumor composed of atypical neoplastic, often pleomorphic cells that invade other tissues. "PARVB has a broad spectrum of biological actions during cancer development, but its mechanistic exploration in GBM has been less studied and was therefore chosen for further study." (PMID 34568031, 2021). "Similarly, IHC analyses performed in this study also revealed lower staining intensities for ParvB in cancer cells relative to normal urothelium cells." (PMID 20736946, 2010). "It remains unknown if ParvB expression levels in various cancers are related to patient survival." (PMID 20736946, 2010).
PARVB also shares sentences with these, for which no sentence is quoted: infection (2 papers); bipolar disorder (1); breast tumors (1); diabetes (1); glioma (1); intellectual impairment (1); neuroblastoma (1); rectum adenocarcinoma (1); Stroke (1).